TNKS (tankyrase)
Diseases named in the same sentence as TNKS in open-access papers (continued):
Sharing a sentence is not in itself a finding about the gene and the disease.
cancer (continued). "Another group of molecules emerging as potential cancer therapeutics are tankyrase inhibitors, which prevent the destruction of Axin, therefore reducing canonical WNT signaling." (PMID 36675309, 2023). "Tankyrase-specific inhibitors have been investigated as a potential therapeutic target in β-catenin–dependent cancers." (PMID 35362478, 2022). "The inhibition of tankyrase (TNKS) activity can reduce cancer cell growth, invasion, and resistance to treatment by blocking the Wnt signaling pathway." (PMID 35052822, 2022). "The therapeutic potential of TNKS inhibition has been widely studied in several types of cancer, but the cardiovascular potential of TNKS inhibition has remained unexplored." (PMID 36077457, 2022). "Treatment with TNKS inhibitors leads to reduced proliferation of cancer cells in Wnt-dependent tumors and mice are frequently used as model organisms in preclinical studies." (PMID 36421702, 2022). "Our findings are of particular importance for the development of novel tankyrase (PARPs 5a and 5b) inhibitors for cancer therapy." (PMID 33801950, 2021). "In this study, we report that Wnt inhibition, via either PORCN or tankyrase inhibition, sensitizes diverse cancers to the PARP inhibitor olaparib." (PMID 33660437, 2021). "The proteins targeted by TNKS include vinculins, that anchor F-actin to adherens junctions (AJ), structures involved in cancer development, while TNKS inhibitors prevent the assembling of AJ." (PMID 34639169, 2021). "Nevertheless, there is a growing knowledge concerning the use of TNKS inhibitors in other types of cancer." (PMID 33910596, 2021). "In this optic, tankyrase promotes Wnt signaling, while TNKS inhibitors are useful in the treatment of Wnt-driven cancers." (PMID 34639169, 2021). "Since E7449, a dual inhibitor of PARP 1/2 and TNKS, is the only drug currently under clinical trials, TNKS inhibitors need to be continuously developed and studied as anticancer drugs to elucidate the biological aspects of cancer cells." (PMID 34298950, 2021). "Tankyrase inhibition can inhibit proliferation and viability in a subset of cancer cell lines in vitro." (PMID 32332858, 2020). "Studies of TNKS inhibitors in cancer cells, including G007-LK, have shown that inhibiting TNKS regulates Hippo signaling." (PMID 32575464, 2020). "The overexpression of TNKS-1/2 has been reported to induce telomere elongation in human cancer cells." (PMID 32268564, 2020). "Another class of WNT inhibitors that has shown efficacy in the treatment of WNT-related cancers are Tankyrase inhibitors." (PMID 31382613, 2019). "It has previously been shown that TNKS inhibition sensitizes KRAS mutant cancer cells to growth inhibition by MEK inhibitors, also in cell lines whose proliferation rate is unaffected by single TNKS inhibitor treatment." (PMID 30717152, 2019). "Altered tankyrase expression has been witnessed in different cancers, comprising fibro-sarcoma, glioblastoma, ovarian cancer, pancreatic adenocarcinoma, gastric cancer, breast cancers, bladder cancer, and colon cancer." (PMID 30932078, 2019). "The Wnt-inhibitor anti-cancer drug (LDW639) targeting tankyrase 1 and 2 (TNKS1/2) in the Wnt/β-catenin signaling pathway was selected as the model system for the CRAM reactor." (PMID 31850321, 2019). "The anti-cancer effects of tankyrase inhibitors are mainly due to their suppression of Wnt signaling and inhibition of telomerase activity, which are mediated by AXIN and TRF1 stabilization, respectively." (PMID 30813388, 2019). "In Wnt-dependent cancers, tankyrase inhibitors exert anti-cancer effects by inhibiting the proliferation of cancer cells." (PMID 30813388, 2019). "The results from previous studies showed the high effectiveness of TNKS inhibitors in inhibiting various cancer cell proliferation including CRC." (PMID 30260955, 2018).
cancer (continued). "Tankyrase thus functions as a positive regulator of the Wnt signaling pathway, and the development of tankyrase inhibitors as potential anticancer drugs for Wnt-driven cancer is under investigation." (PMID 30533199, 2018). "In the present study, we found that tankyrase inhibitors sensitized cancer cells to DNA-damaging anticancer drugs." (PMID 30533199, 2018). "Recently a lot of effort has been put into developing more potent and selective TNKS inhibitors and optimizing them towards anti-cancer agents." (PMID 29374194, 2018). "Tankyrase also plays a role in regulating the mitotic spindle, centrosome maturation and cancer cell invasion by its interaction with NuMA, MIKI and TNKS1BP1, respectively." (PMID 30533199, 2018). "This is consistent with a plethora of studies showing that TNKS inhibitors suppress cell proliferation in several cancer cell lines." (PMID 30260955, 2018). "Additional studies would clarify the relationship of tankyrase inhibitor sensitivity to cancer stemness." (PMID 28615517, 2017). "In vitro and in vivo studies have demonstrated the excellent efficacy of these Tankyrase inhibitors for cancer treatment." (PMID 28877210, 2017). "Another novel approach of inhibition of telomerase activity in cancer cells relies on the inhibition of tankyrase-1, which shortens telomeres in cancer cells and initiates DDRs." (PMID 28218725, 2017). "Tankyrase-mediated degradation of HectD1 or NKD2 would have a similar impact on cancer cell growth as degradation of Axin, to stabilize β-catenin and promote growth." (PMID 29263426, 2017). "While tankyrase inhibition appears to be a viable approach in cancer therapeutics, several groups have reported challenges with the use of XAV939 in their preclinical tumor models." (PMID 26246473, 2015). "Wnt/β-catenin signaling has been identified as a potential mediator of resistance to MEK inhibition and strong synergy has been observed for the combination of MEK and tankyrase inhibition in KRAS-mutant cancer cells." (PMID 26513298, 2015). "Tankyrase is a key regulator of Wnt/β-catenin signaling, a pathway known to promote tumorigenesis and a target for the development of cancer therapeutics." (PMID 26513298, 2015). "As such the compound is an excellent biological probe for the evaluation of the effects of tankyrase inhibition in different cancer cell lines." (PMID 23762361, 2013). "The compound, WIKI4, was found to act through tankyrase inhibition and regulate β-catenin levels in many cancer cell lines and human embryonic stem cells." (PMID 23762361, 2013). "There is a paucity of literature on differential TNKS expression at either the mRNA or the protein level in cancer." (PMID 23621985, 2013). "The rationale for using tankyrase inhibitors in cancer therapy comes from its various functions within the cell." (PMID 23762361, 2013). "We provide the first evidence for regulation of DNA-PKcs by tankyrase 1 PARP activity and taken together, identify roles of tankyrase 1 with implications not only for DNA repair and telomere biology, but also for cancer and aging." (PMID 21037379, 2010). "In these reports, NuMA was found to be important for cell survival, and in mitosis it was found to interact with tankyrase 1 and to contribute to the formation of multipolar spindles in cancer cells." (PMID 19400937, 2009). "TNKS-2 and its close homolog TNKS-1 are positive regulators of telomere elongation, which is important for the perpetual growth of cancer cells." (PMID 19270793, 2009). "Tankyrase 1 modulates telomerase inhibition in human cancer cells and is reviewed in this report as a potential telomere-directed anticancer target." (PMID 16421589, 2006). "This minireview describes some potential problems with telomerase inhibitors and introduces the telomeric poly(ADP-ribose) polymerases (PARP), tankyrase 1 and 2, as the second potential target for telomere-directed molecular cancer therapeutics." (PMID 16421589, 2006).
cancer (continued). "Multiple functions of tankyrases in accordance with a variety of binding partners pose the next challenging question about potential side effects of tankyrase-directed cancer therapy." (PMID 16421589, 2006). "Additionally, both in vitro and in vivo studies showed that inhibition of tankyrase repressed tumorigenesis by activating LKB1 and AMPK, providing further evidence for the potential of tankyrase inhibitors as anti-cancer drugs." (PMID 40134437, 2025). "Therefore, discovery of clinical-grade tankyrase inhibitors has been prioritized as a potential anti-cancer therapeutic strategy with several compounds examined in pre-clinical studies." (PMID 40061138, 2025). "Tankyrase inhibition, coupled with emerging insights into PARdU signaling, represents a cornerstone of precision oncology, offering transformative potential in cancer therapy." (PMID 40001540, 2025). "Taking our results into account for the further development of tankyrase inhibitors as candidate drugs for cancer therapy, it is crucial that future studies go beyond its use as a Wnt/β-catenin inhibitor and address this interplay in different cell types and organ systems." (PMID 37741944, 2024). "Consequently, tankyrase small-molecule inhibitors block Wnt signaling by stabilizing axin, revealing potential for cancer therapy." (PMID 37721093, 2023). "Therefore, inhibition of TNKS is considered as a novel method for malignant tumor treatment by blocking the Wnt signaling pathway." (PMID 35450028, 2022). "Since the Arpin and TNKS levels vary in opposite directions in cancers, the interaction between Arpin and TNKS reported here might be more important in the regulation of cell migration in untransformed cells than in tumor cells." (PMID 33923443, 2021). "Their activity in the β-catenin destruction complex can be increased by tankyrase inhibitors, which thus may serve as a therapeutic option to reduce the growth of β-catenin-dependent cancers." (PMID 33811251, 2021). "With the advent of novel inhibitors of TNKS, TNKS can act as a novel target in various cancers." (PMID 31897238, 2020). "Interestingly, the treatment of colorectal xenograft cancers using the Tankyrase inhibitor NVP-TNKS656 led to overcoming WNT-mediated drug resistance." (PMID 31382613, 2019). "Such compounds will enable probing the scaffolding functions of tankyrase, and may, in the future, provide potential alternative therapeutic approaches to inhibiting tankyrase activity in cancer and other conditions." (PMID 31836723, 2019). "Tankyrase has attracted attention as a novel and promising target for cancer treatments." (PMID 30813388, 2019). "Aberrant overexpression of TNKS plays important roles in a several cancers." (PMID 30915350, 2019). "Indeed, various small-molecule tankyrase inhibitors have been synthesized and confirmed to have anti-cancer effects on a wide range of cancers, including colon, breast, lung, prostate, ovarian, and liver, as well as osteosarcoma." (PMID 30813388, 2019). "Flavones are known as an inhibitor of tankyrase, a potential drug target of cancer." (PMID 30932078, 2019). "To investigate the mechanisms underlying the tumorigenic function of TNKS, we examined whether TNKS1 affected aerobic glycolysis, which is one of the hallmarks of cancer." (PMID 30915350, 2019). "Therefore, tankyrase inhibition offers a reasonable approach for cancer therapy, and as a result, the treatment of cancer cells in combination with telomerase and ARTD inhibitors leads to telomere shortening and cell death." (PMID 30932078, 2019). "Tankyrase inhibitors exert their anti-cancer effects through multiple mechanisms." (PMID 30813388, 2019). "In another example, since tankyrase knockout results in defective mitotic spindles, inhibitors could be used in conjunction with mitotic inhibitors or spindle poisons to kill cancer cells." (PMID 29263426, 2017). "shRNA against tankyrase 1 has been shown to reduce cell viability in cancers." (PMID 28218725, 2017).
cancer (continued). "Considering that Notch signaling is commonly activated in cancer, tankyrase inhibitors may have therapeutic potential in targeting this pathway." (PMID 29263426, 2017). "Whether a sufficient therapeutic window exists between TNKS inhibition in cancer cells and normal cells is still an open question, as is the toxicity profile of the class." (PMID 23621985, 2013). "Our results show in vivo anti-cancer effects of TNKS knockdown." (PMID 23621985, 2013). "Later, TNKS2 was discovered and multiple roles of tankyrases in various cellular signaling pathways have implied that tankyrase inhibitors could be potential drugs especially towards different forms of cancer." (PMID 23762361, 2013). "That study suggested that tankyrase inhibition could induce cancer progression." (PMID 40134437, 2025). "Therefore, TNKS inhibitors may be developed as novel anti-cancer drugs mining the Wnt signaling pathway." (PMID 38731421, 2024). "Discovery of K11 ubiquitylation that opposes degradation, along with identification of multiple PAR-binding E3 ligases that ubiquitylate tankyrase, provide insights into mechanisms of tankyrase regulation and may offer additional uses for tankyrase inhibitors in cancer therapy." (PMID 37938264, 2023). "Consequently, tankyrase inhibitors are considered as promising therapeutics for cancer treatment." (PMID 36677673, 2023). "Therefore, TNKS inhibition has emerged as an attractive strategy for cancer therapy." (PMID 34298950, 2021). "The inhibition of TNKS sustained the life of axin and surged the extent of the devastation complex of β-catenin, which led decrease levels of β-catenin and increased the levels of phosphorylated β–catenin triggering inhibition of the Wnt/β-catenin driven proliferation of cancer cells." (PMID 30932078, 2019). "Through precise modelling of cancer-associated mutations using cytidine base editors, we show that this therapeutic approach is absolutely dependent on suppression of canonical WNT signaling by TNKS inhibitors and is effective in cells from multiple epithelial cancer types." (PMID 31891587, 2019). "Thus, the therapeutic relevance of inhibiting the Wnt pathway in cancer remains, and multiple drugs that inhibit Wnt signaling are showing promise for clinical application (e.g., inhibitors of Wnt secretion, tankyrase 1/2 inhibitors, and inhibitors of β-catenin interactions)." (PMID 27729975, 2016). "Thus, antagonizing the Wnt pathway through TNKS inhibition may serve to overcome drug resistance in the cancer stem cell niche and thereby reduce outgrowth of these intrinsically drug-resistant cells." (PMID 23621985, 2013). "TNKS1 was discovered as an enzyme controlling the length of human telomeres and this was the first implication that tankyrase inhibitors could be useful as therapeutic agents against cancer." (PMID 23762361, 2013). "Although enzymatic inhibitors of tankyrase (TNKS) effectively block AXIN degradation and stabilize the β-catenin destruction complex (DC), they have demonstrated limited efficacy in various cancer models." (PMID 41040241, 2025). "Collectively, these findings provide an explanation for the unsatisfactory outcomes of drugging the WNT/β-catenin signaling pathway by TNKS inhibitors and highlight TNKS degradation as a promising approach to treat WNT/β-catenin-driven cancers." (PMID 41040241, 2025). "To investigate the role of the YAP/TAZ-TEAD system in the control TRAIL sensitivity, we initially assessed the effect of the tankyrase inhibitor XAV939, a well-known inhibitor of TEAD activity, in the apoptotic response of cancer cells to TRAIL." (PMID 37830584, 2023). "Despite this, the tankyrase inhibitors E7449 and STP1002 have entered clinical trials in the cancer arena." (PMID 36873622, 2022). "Tankyrases (TNKS, TNKS2) are proteins involved in telomere length maintenance, which, together with regulation of the Wnt/β-catenin pathway, is important for cancer cell renewal and survival." (PMID 36142793, 2022).
cancer (continued). "Hence, providing a novel TNKS inhibitor strategy may be beneficial for combating related cancers." (PMID 35052822, 2022). "One TNKS partner, TNKS1BP1, which is PARylated, negatively regulates cancer cell invasion by interacting with the capping protein and decreasing the actin filament dynamics." (PMID 33923443, 2021). "TNKS, which degrades AXIN in the β-catenin destruction complex, has been suggested as an attractive target for cancer therapy." (PMID 34298950, 2021). "Tankyrase enzymes (TNKS), a core part of the canonical Wnt pathway, are a promising target in the search for potential anti-cancer agents." (PMID 32664504, 2020). "The consequence examples are, IWR-1 and IWR-2 which are tankyrase inhibitors and stabilize AXIN and inhibit WNT signaling and proliferation in APC-null DLD1 cancer cells." (PMID 30932078, 2019). "Taken together, these findings suggest that tankyrase and RNF146 are major up-stream regulators of LKB1-AMPK pathway and provide another focus for cancer and metabolic disease therapies." (PMID 31554794, 2019). "Currently, the anti-cancer efficacy of XAV939 and other tankyrase inhibitors has been evaluated in preclinical in vitro and in vivo studies." (PMID 30185973, 2018). "As many cancers are dependent on WNT signalling, the inconsistency in reported results justifies further investigation of the toxicity and effects of tankyrase inhibitors, such as G007-LK, in preclinical and clinical studies." (PMID 29316982, 2018). "Through the analysis of these resistant cells, we identified the mTOR pathway, an important proliferation factor in various cancers including CRC, as a crucial resistant factor to tankyrase inhibitors." (PMID 28615517, 2017). "Tankyrase 1 and 2 are poly(ADP-ribose) polymerases that function in pathways critical to cancer cell growth." (PMID 29263426, 2017). "The poly(ADP-ribose) polymerase (PARP) Tankyrase (TNKS and TNKS2) is paramount to Wnt-β-catenin signaling and a promising therapeutic target in Wnt-dependent cancers." (PMID 27494558, 2016). "Preclinical studies with tankyrase inhibitors JW55 (Tocris Bioscience) and XAV939 (Novartis Pharmaceuticals) demonstrated efficacy in cellular models of cancer survival." (PMID 27226375, 2016). "Our present study showed that SMA fulfils anti-cancer agent criteria for inhibiting genetically heterogeneous cancers by inhibiting both PI3K/Akt and tankyrase, which is a regulatory component of GSK3β activity." (PMID 26544726, 2015). "It has also been reported tankyrase 1 is overexpressed in a variety of cancers, and XAV939 has been shown to be an effective anti-cancer agent for CRC and other cancers." (PMID 26544726, 2015). "The inhibition of Tankyrase 1, a member of PARP family, in human cancer cells, has been shown to enhance telomere shortening and hasten cell death." (PMID 20678253, 2010). "Moreover, whereas AXIN1 is tightly controlled by tankyrase‐mediated PARsylation and ubiquitination, DCAF7 up‐regulation tracks with copy‐number gain and epigenetic/RNA‐modification changes in our pan‐cancer analysis." (PMID 41472554, 2026). "Tankyrase is a member of the poly(ADP-ribose)polymerase family which mediates Wnt signal transduction and has emerged as a new molecular target for the therapy of different kinds of cancer." (PMID 36677673, 2023). "Preclinical studies in several cancer models show promising results, however, no tankyrase inhibitors are currently in clinical trials." (PMID 36675309, 2023). "Since much is known about PARP1-3 and the Tankyrases (PARP5a/5b), this review will focus on the lesser-studied PARP family members, their roles in maintenance of genomic stability and cellular homeostasis, and their potential as cancer targets." (PMID 35096828, 2021). "Tankyrase inhibitors have been also developed as a therapeutic alternative to treat cancer, although there are no current clinical trials studying them." (PMID 33910596, 2021).